LEP (leptin)
Diseases named in the same sentence as LEP in open-access papers (continued):
Sharing a sentence is not in itself a finding about the gene and the disease.
Obesity (continued). "The impact of obesity was also indicated by the trend of higher level of leptin observed in this subgroup of PHP1 patients compared to normal controls." (PMID 38017461, 2023). "The proliferative capacity of lymphocytes was only similar between the eutrophic and obesity groups in the presence of adiponectin and melatonin + leptin (p < 0.05)." (PMID 36768983, 2023). "In periodontitis, leptin levels increase with a reduction in adiponectin levels, similar to what occurs in obesity." (PMID 36980434, 2023). "Leptin is one of the obesity adipokines that accelerate the proliferation of CRC and also elevates insulin concentration." (PMID 36982300, 2023). "Similar to Se supplementation, Zn supplementation has also been found to positively affect insulin resistance and leptin levels in people with obesity." (PMID 37513551, 2023). "Leptin is thought to be an attractive treatment for obesity due to its role in controlling appetite." (PMID 37603580, 2023). "Acupuncture seems to affect many biochemical markers of obesity such as lipid metabolism, obesity-related peptides (e.g. leptin, ghrelin) and inflammatory markers." (PMID 37789716, 2023). "Subclinical inflammation and oxidative stress in obesity lead to leptin resistance that results in low LH and low testosterone, which is one of the causes of ED." (PMID 37790032, 2023). "Leptin is a hormone produced in fat tissue and then released to the bloodstream in relation to fat mass to exert anti-obesity effects." (PMID 37661748, 2023). "Similarly, obesity was already associated with a higher risk of induction failure, a higher risk of CS, and prolonged labor due to impaired uterine contractility, potentially caused by altered cholesterol levels, increased leptin concentration, and hormonal imbalance." (PMID 37415612, 2023). "SOCS3 is an inhibitor of STAT3, an important marker of leptin signaling as deletion of the STAT3 gene in the CNS induces obesity." (PMID 37571301, 2023). "This inhibition reduces the responsiveness of POMC neurons to leptin, ultimately contributing to overeating and the development of obesity." (PMID 38027481, 2023). "The effects of leptin/obR signaling on obesity-related neutrophilic airway inflammation were reversed upon treatment with an obR antagonist (Allo-Aca) or absent in db/db mice (obR-b deficiency)." (PMID 37488474, 2023). "Acute inhibition of GIPR using neutralizing antibodies has shown the ability to substantially reduce body weight and improve obesity by enhancing the effectiveness of leptin." (PMID 37957462, 2023). "In studies conducted on people with obesity, serum leptin / adiponectin levels were found to be significantly higher in women than in men." (PMID 36765298, 2023). "We genotyped rs10487505 in DNA samples from 1665 patients with obesity and lean controls and measured leptin gene expression in paired samples of adipose tissue (AT, N = 310), as well as circulating leptin levels." (PMID 36833305, 2023). "Leptin and adiponectin play a role in the pathogenesis of obesity-related lung diseases by affecting systemic inflammation, regulatory T (Treg) cell activity, and T helper cell 17 (Th17) and T helper cell 2 (Th2) immune responses." (PMID 38001499, 2023). "Inhibition of PTP1B in neurons resolved leptin resistance, glucose disorders, and obesity induced by over-nutrition." (PMID 36899905, 2023). "In animal models, supplementation with physiological doses of leptin during the suckling period in offspring of normal-weight dams has been shown to improve metabolic health and prevent the development of obesity and related disorders later in life." (PMID 36771278, 2023). "Blockade of LepR in the DMH prevented the activation of BAT by leptin, implicating a role for this hypothalamic site in the sustained thermogenic effects of leptin during obesity." (PMID 36769012, 2023). "Obese individuals are likely to develop leptin resistance, resulting in greater food intake perpetuating the progression of obesity." (PMID 37920118, 2023).
Obesity (continued). "It was found that those with obesity began with leptin levels higher than 31 ng/mL, and after 24 h of fasting, levels decreased to around 12 ng/mL." (PMID 37049602, 2023). "As independent PON-1 predictors, TBARS, leptin, and adiponectin levels demonstrate the significance of obesity in the control of PON-1." (PMID 37107203, 2023). "It has been reported that high leptin concentration in obesity inhibits Leydig cells function and, thus, testosterone synthesis." (PMID 37629396, 2023). "In murine models of obesity, leptin accumulates in the median eminence and experimental activation of ERK signaling restores its transport." (PMID 36674935, 2023). "Conversely, overexpression of FoxO1 in the hypothalamus impairs leptin signaling and leads to hyperphagic obesity." (PMID 38027481, 2023). "Leptin levels are not only naturally elevated in obesity but also genetic ablation of leptin gene can induce obesity." (PMID 37128293, 2023). "A longer irradiation time must have allowed the Ce6 photosensitizer to penetrate deeper into the adipose tissue, allowing for a greater reduction in body weight and other obesity markers like leptin." (PMID 37513964, 2023). "Our results demonstrate leptin/obR signaling plays an important role in the pathogenesis of obesity-related neutrophilic airway inflammation in females by promoting M1 macrophage polarization." (PMID 37488474, 2023). "In this essay, we will examine how imbalances in insulin and leptin can lead to obesity and diabetes." (PMID 37600709, 2023). "This is the first study comparing the maternal metabolome in the first trimester of pregnancy considering proxies of obesity (BMI) and adiposity (leptin) as well as of the glucose-insulin axis (glucose, C-peptide, ISHOMA)." (PMID 37029207, 2023). "Ghrelin decreases and leptin increases in obese subjects, which is considered a physiological adaptation to obesity." (PMID 37355724, 2023). "Obesity also alters the levels of adipokines like leptin and adiponectin, which are crucial in regulating reproductive hormones and menstrual cycles." (PMID 38264286, 2023). "In tandem with the progression of obesity resultant from increased adipose tissue mass, an accompanying significant increase in circulating levels of leptin is observed and correlates positively with total body weight and adiposity." (PMID 37629396, 2023). "Food intake rapidly decreases plasma ghrelin concentrations and a decrease in ghrelin concentrations are accompanied by a simultaneous increase in leptin concentrations during obesity." (PMID 37174575, 2023). "Chronic inflammation and elevated TNFα levels in individuals with obesity and leptin resistance contribute to hyperleptinemia." (PMID 37755259, 2023). "In line with the existing literature, our findings from pre- and post- surgical evaluations showed a relationship between MetS and severe initial obesity resulting from increases in leptin levels and reductions in adipose levels." (PMID 37571250, 2023). "DRP1-mediated mitochondrial fission negatively regulates POMC neuronal responses to glucose and leptin sensitivity contributing to obesity and diabetes development." (PMID 37174622, 2023). "As we found striking changes of the manifestations of schistosomiasis in obese mice, determinant factors of obesity such as proinflammatory cytokines, leptin, and adiponectin have to be investigated." (PMID 37296126, 2023). "Knockdown of ROCK1 expression in healthy mice led not only to excessive food intake, dyslipidemia, and obesity, but also hyperleptinemia (leptin is an effective adipokine) (Landry, Shookster & Huang, 2021)." (PMID 37304877, 2023). "Since adipose tissue is metabolically active and secretes estrogens, adipokines (such as leptin) and secrete cytokines, a tight connection has been established between obesity and cancer (Lumeng, Bodzin & Saltiel, 2007)." (PMID 37155466, 2023).
Obesity (continued). "Although leptin’s primary function is to regulate body weight in the long term, leptin resistance occurs in obesity and its concentrations correlate positively with the lipid markers of inflammation and atherosclerosis in asymptomatic T2DM." (PMID 37512134, 2023). "Slug recruits epigenetic modifiers to induce repressive epigenetic modifications on the LepRb promoter/enhancer, resulting in suppression of LepRb expression, leptin resistance, and obesity." (PMID 36512408, 2023). "The fast food and meat pattern were the first factor extracted, explaining 11–13 % variation of the obesity-related response variables (BMI, total body fat and visceral fat), leptin and adiponectin showed the lowest percentage (4·5–0·1 %)." (PMID 37231745, 2023). "As we observed in this study, patients with overweight or obesity had the highest serum leptin and free leptin levels, while malnourished patients had the lowest concentrations." (PMID 36967775, 2023). "Understanding these intricate neural networks is essential for formulating targeted strategies that leverage leptin to combat obesity effectively." (PMID 38027481, 2023). "Due to the characteristic of adiponectin/leptin ratio in obesity in general, there is strong possibility that the ratio would also serve as an excellent marker for pancreatic cancer, similar to IL-6/IL-8 ratio, for tracking inflammation for clinical purposes." (PMID 37181043, 2023). "Failure to produce leptin or the development of leptin resistance can contribute to the development of obesity due to the body’s inability to maintain energy homeostasis." (PMID 37626804, 2023). "The purpose of this systematic review is to analyze the effects of adiponectin and leptin on the brain and how they correlate to the development of cognitive decline in obesity." (PMID 37363537, 2023). "Leptin and adiponectin are adipokines secreted by adipose tissue that play a role in regulating metabolism and are important links between obesity and metabolic syndrome." (PMID 37711898, 2023). "In this sense, a critical role of leptin during lactation in the protection against the development of obesity-related metabolic alterations in adulthood has been demonstrated, particularly in animal models." (PMID 36771278, 2023). "Previous research confirmed that age-related changes in the central anorexigenic and hypermetabolic responsiveness to leptin appear to promote middle-aged obesity." (PMID 37240340, 2023). "Human pancreatic cancer also exhibited chemoresistance to anticancer drugs due to obesity and leptin signaling." (PMID 37893166, 2023). "In this context, the correlation between the obesity hormone leptin and CRC has been studied in recent years." (PMID 36981858, 2023). "The function of the leptin used was independently validated, given that the same treatment effectively reduced obesity in ob/ob mice and dramatically increased p-STAT3 expression in the Arc." (PMID 37069175, 2023). "The results are consistent with other studies, confirming the effect of obesity on increasing leptin levels." (PMID 36520252, 2023). "The long-term co-administration with L-penetratin was confirmed to increase leptin levels in the OB and hypothalamus, the latter being the target of leptin treatment of obesity." (PMID 37371113, 2023). "This alteration was defined as the “leptin paradox”, a phenomenon in which hamsters become almost unsensitive to this hormone (similar to what happens in obesity) during LP, whereas leptin sensitivity strongly increased during SP." (PMID 36674520, 2023). "Impairment of ciliary structure and signaling appears to contribute to leptin resistance in obesity pathology." (PMID 37064917, 2023). "In fact, low levels of ω-3 fatty acids and high levels of leptin have been reported in subjects with obesity, which are related to a proinflammatory state." (PMID 38137540, 2023).
Obesity (continued). "Raut and coworkers also demonstrated that adiponectin, an adipokine severely diminished in obesity that exerts anti-inflammatory and antitumor actions, completely suppressed leptin-induced NLRP3 inflammasome activation." (PMID 37819510, 2023). "Leptin, a metabolic factor that increases in obesity, has been reported to be involved in preeclampsia." (PMID 36768469, 2023). "Genetic variants included in the GRS for weight development after BS usually include hypothalamic genes related to monogenic obesity, involved in the regulation of energy homeostasis, mainly the hypothalamic leptin-melanocortin system." (PMID 37445323, 2023). "Hypoxia further causes an inflammatory response that inhibits ADP expression, while increasing the secretion of LEP and related inflammatory factors, which is proportional to obesity, glucose tolerance, and the degree of insulin resistance." (PMID 37181308, 2023). "Firstly, six key adipokines known to be deregulated in obesity and related metabolic and vascular complications are described, namely adiponectin, leptin, resistin, IL-6, MCP-1 and PAI-1." (PMID 38136564, 2023). "While leptin has effects on the central nervous system to stimulate satiety and energy expenditure, an increase in the circulating levels with obesity can lead to leptin resistance, resulting in the activation of immune cells." (PMID 37372149, 2023). "Obesity and asthma enhance the pro-inflammatory state in the body because high levels of leptin stimulate Th1 response, and low levels of adiponectin inhibit IL-10 secretion." (PMID 36767041, 2023). "In boys and girls with obesity, leptin is elevated throughout puberty with a tendency to increase in girls and decrease in boys, probably due to the effect of androgens." (PMID 37299398, 2023). "In obesity treatments, normalizing leptin sensitivity has been proposed as a strategy to increase weight loss and prevent weight regain." (PMID 37238961, 2023). "A more comprehensive understanding of the neuronal networks and circuits that respond to leptin will facilitate the development of novel strategies to alleviate leptin resistance and counteract obesity." (PMID 38027481, 2023). "Db/db mice, which lack the receptor for leptin, rapidly develop obesity on the standard chow diet and exhibit AHR starting at 8 weeks, even in the absence of any inciting exposure." (PMID 36599824, 2023). "Obesity and MetS are characterized by decreased serum adiponectin in parallel with increased concentrations of circulating leptin." (PMID 36920931, 2023). "Obesity increases the amount of adipose tissue and serum leptin levels, thereby decreasing leptin sensitivity." (PMID 36843597, 2023). "Leptin is a product of obesity, plays an important role in regulating food intake, body weight, and lipolysis, and is positively correlated with leptin content." (PMID 36742427, 2023). "Considering that serum leptin concentration is markedly associated with BMI and that it has been found in our study to be inversely associated with total taste scores, it could be pointed as one of the underpinnings of the sweet sensitivity decrease often found in patients with obesity." (PMID 38313840, 2023). "The concept of selective leptin resistance was first identified in the context of leptin-induced activation of the sympathetic nervous system and its contribution to obesity-induced hypertension." (PMID 36769012, 2023). "We monitored glucose and leptin levels as indicators of obesity due to the provision of HFD for 10 weeks." (PMID 36899958, 2023). "Adipose tissue remodeling associated with obesity alters the synthesis of adipokines such as tumor necrosis factor (TNF-α), leptin, and adiponectin." (PMID 36991247, 2023). "Obesity from childhood to adolescence predicts increased asthma incidence, potentially due to elevated proinflammatory serum leptin levels." (PMID 37772245, 2023).
Obesity (continued). "The deletion of Mfn2 in the anorectic pro-opiomelanocortin (POMC) neurons of the hypothalamus disrupts endoplasmic reticulum (ER)–mitochondria contacts, ER stress activation, leptin resistance, and obesity." (PMID 36677011, 2023). "Particularly, evidence indicates that the majority of the anti-obesity effects of leptin are mediated by the GABAergic AgRP neurons." (PMID 36674520, 2023). "Studies that correlate obesity among children in Palestine with hypertensive disorders, diabetes mellitus, leptin, and lipid profiles have found a strong relationship between being overweight and obese." (PMID 37533576, 2023). "In parallel, obesity-related adipose tissue actively participates in the synthesis of inflammatory factors such as leptin and resistin, while concurrently inhibiting the secretion of anti-inflammatory mediators like adiponectin." (PMID 37834123, 2023). "First, previous studies have suggested that exposure to O3 could stimulate the synthesis and secretion of leptin by activating lipopolysaccharides and the hypothalamus pituitary adrenal axis and increasing the release of fasting fatty acids, which may be associated with subsequent obesity." (PMID 37876545, 2023). "In contrast, in obesity, the pathological adipose tissue expansion, with hypertrophy of adipocytes, unbalance that pattern, and the obese adipose tissue releases more leptin and less adiponectin." (PMID 36831188, 2023). "Some genetic alterations in specific molecules, especially in children, can lead to obesity, such as those affecting leptin, pro-hormone convertase 1/3, congenital melanocortin-4 receptor deficiency, and GNAS gene mutations." (PMID 38139229, 2023). "Adiponectin and Leptin are essential for the onset of metabolic disorders, such as diabetes and obesity, and their expressions are regulated by the methylation level in promoters." (PMID 36829148, 2023). "According to a previous study, BPA has been shown to increase the level of leptin in adipose tissues, which promotes obesity and inflammatory disorders like hypertension, metabolic syndrome, and cardiovascular disease." (PMID 37324904, 2023). "Fibromyalgia is often comorbid with obesity and metabolic perturbations, such as insulin resistance and elevated leptin." (PMID 36998474, 2023). "In the adipose tissue of individuals with obesity, adipocyte cytokine leptin levels increase, whereas adiponectin levels decrease." (PMID 38029078, 2023). "Amelioration of dyslipidemia status has been assumed to relate to improved insulin sensitivity and leptin modulation, as well as obesity prevention." (PMID 37571314, 2023). "Leptin levels in the blood are directly proportional to the mass of WAT, and obesity leads to high levels of leptin in the systemic circulation." (PMID 37492183, 2023). "Surprisingly, among several circulating factors tested, we only observed elevated levels of leptin in UCB plasma of mothers with obesity." (PMID 36645353, 2023). "The discovery of leptin as a hormone governing body mass and energy balance gave hope for a new approach to the treatment of obesity, involving its administration." (PMID 36978817, 2023). "The gene for SCD-1 is suppressed by leptin, and the suppression of SCD-1 can lead to a considerable loss of weight in people affected by obesity." (PMID 36765351, 2023). "Obesity is exacerbated by leptin resistance, which then contributes to an increase in leptin levels, creating a vicious circle known as “leptin-induced leptine resistance”." (PMID 37238961, 2023). "In the group of adipokines, leptin hormone serves as an indicator of adipose tissue changes and obesity." (PMID 37507988, 2023). "Leptin (Lep) has also been found to be related to obesity–hypertension syndrome, metabolic syndrome (MetS), conditions with moderate association with BMI and several other conditions." (PMID 37240998, 2023).